TNF (tumor necrosis factor)
Diseases named in the same sentence as TNF in open-access papers (continued):
Sharing a sentence is not in itself a finding about the gene and the disease.
cancer (continued). "They secrete cytokines such as interferon-γ and tumor necrosis factor-α (TNF-α), which enhance prognosis by inducing apoptosis and impeding cancer cell proliferation, invasion, and migration." (PMID 39359427, 2024). "A total of 188 signaling pathways were screened out, including cancer pathway, PI3K-Akt, IL-17, and TNF signaling pathway." (PMID 39259113, 2024). "Regarding TNF inhibitors, as per the most recent ECCO guidelines, they are deemed suitable for use in patients with IBD who also have concurrent cancer." (PMID 39272800, 2024). "TNF-α, IFN-γ, IP-10, MIP-1α, MIP-1β and MIP-2 as indispensable immune factors is necessary in regulating anti-cancer immune." (PMID 38813211, 2024). "The results showed that most cancer cell line death was induced by co-treatment of IFN-γ and TNF-α, in which cell death was significantly induced in MC38 and HCT116, they were close to complete death after co-treatment of IFN-γ and TNF-α for 96 h." (PMID 38740747, 2024). "EndMT is initiated by specific inductors secreted by cancer cells, such as TGF-β, IL-1β, tumor necrosis factor-α (TNF-α), NF-kB transcription factor, and endotoxin." (PMID 38602594, 2024). "IL-1β and TNF-α also activate the MAPK pathway, increasing gene expression in those that promote cancer cell growth and inflammation." (PMID 39728433, 2024). "M1-TAMs are classically activated through lipopolysaccharide, IFN-γ, tumor necrosis factor (TNF), GM-CSF, or Toll-like receptor (TLR) ligands, and exhibit pro-inflammatory and anti-cancer properties, releasing various cytokines." (PMID 39408564, 2024). "Upon stimulation, immune cells can secrete effector cytokines, such as TNFα or IFN-γ, to directly provoke the cell death of cancer cells." (PMID 38201300, 2024). "Other pathways have been reported to interact with AMPK in ACTs or in the tumorigenic process of other types of cancer, including the Hedgehog signaling pathway, the MAPK signaling pathway, tumor necrosis factor (TNF), and nuclear factor kappa B (NFKB)." (PMID 38539429, 2024). "Mediated by tumor necrosis factor-alpha (TNF-α), CSN5 can deubiquitinate PD-L1 in cancer cells, maintain its stability, and escape immune surveillance." (PMID 39748950, 2024). "An absence of magnesium in the body can trigger the activation of tumor necrosis factor (TNF), interleukin-1 (IL-1), and IL-6, which can further enhance the likelihood of cancer cell spread." (PMID 38525719, 2024). "TGF-β has been detected in a wide range of cancers, alone or in combination with other immunosuppressive cytokines, such as IL-10, PGE2 and TNF-α." (PMID 39020402, 2024). "In accordance with previous study, we found that the inflammatory factors including ac‐NF‐κB, NF‐κB, and TNF‐α were increased in SIRT6 KO mice, which are important proteins that promotes cancer cell proliferation." (PMID 37936548, 2024). "However, TNFα blockers are not efficacious in all patients, have been implicated in the susceptibility to some cancers, and may induce intolerable immunosuppression." (PMID 39867889, 2024). "The probability of cancer in the SSc group with TNF α ≥ 7.91 pg/mL was 29%, whereas in those with TNFα < 7.91 pg/mL was 0% (p = 0.002)." (PMID 38051374, 2024). "In line with this, gene therapy techniques that involve the use of adenoviruses as transfer vectors expressing TNF-α, IL-2, IL-12, IFN-a2b, IFN-β, or GM-CSF have been used to modulate cytokine expression in several cancer indications." (PMID 38256080, 2024). "Elevated levels of proinflammatory cytokines, such as interleukin 6 (IL-6) and tumor necrosis factor alpha (TNF-α), are known to enhance cancer cell proliferation and survival." (PMID 38610685, 2024).
cancer (continued). "Our results show that TGF-β/TNF-α combined treatment of the cancer cells synergistically increased the expression of MMP-2 and MMP-25 when we compared either treatment of TGF-β or TNF-α." (PMID 39351229, 2024). "The activation of GMPS can mediate the production of inflammatory cytokines, INF-α, and tumor necrosis factor (TNF), thus activate STAT and NF-κB pathways in cancer cells, stimulate their growth, and increase chemotherapy resistance." (PMID 38270700, 2024). "Another study found that TNF-α and IFN-γ were able to induce PANoptosis in 13 different human cancer cell lines from colon, lung, melanoma, and leukemia, through the activation of GSDMD, GSDME, caspase-8, caspase-3, caspase-7 and MLKL." (PMID 38877579, 2024). "NF-κB is well understood to be involved in many molecular processes, such as IL-6, TNF-α, and TLR4, in cancer." (PMID 38997762, 2024). "The mechanism of the anticancer-based action of 4-TZDs is focused mainly on cancer-related biotargets, e.g., JNK simulating phosphatase-1 (JSP-1) protein, tumor necrosis factor α (TNFα), and/or anti-apoptotic bio-complex (Bcl-XL-BH3)." (PMID 38920636, 2024). "In contrast, the angiostatic cytokine profiles of TNFα, MIG, M-CSF, IL-10, and IFNγ in the host serum revealed a dramatic and significant decrease after day 5 post-implantation of cancer cells." (PMID 39451257, 2024). "Tumor Necrosis Factor-alpha (TNF-α) is a multifunctional cytokine that provides resistance to infections, inflammation, and cancer." (PMID 38965280, 2024). "TNF-α induced a significant increase in the secretion of chemokines and cytokines from CT26 cancer cells including CCL2, CCL3, CCL4, CCL5 and G-CSF." (PMID 39310770, 2024). "It is also possible that acetate affects inflammation, such as lowering NF-κB and TNF-α in animal experiments, which has a complex role in IHD and cancer." (PMID 39519507, 2024). "These cells express the T-box transcription factor TBX21 (T-bet) and are responsible for generating anti-cancer elements such as IFN-γ, IL-2, and TNF-α." (PMID 38835055, 2024). "Although the sensitivity of individual cancer cell lines to TNF‐α and IFN‐γ varied, the combination treatment was shown to have the ability to broadly induce cancer cell death." (PMID 38069556, 2023). "Aromatase is induced in adipocytes by pro-inflammatory factors (such as IL6, TNFα) and adipokines (such as leptin), secreted by the adipocytes themselves, or by other cytotypes in the TME, including inflammatory cells and cancer cells themselves." (PMID 37561190, 2023). "In both cancer patients and non-cancer-afflicted subjects, IL-4, IL-5, IL-12p70, IL-17, IFN-α, and TNF-α all trended to significantly decrease at the early stage and markedly increase at the late stage of Omicron infection." (PMID 37035158, 2023). "KEGG pathway was enriched in 150 related pathways, suggesting that A. cantoniensis Hance acts on cancer signaling pathway, endocrine resistance pathway, PI3K-AKt signaling pathway, MAPK, TNF and other signaling pathway." (PMID 37035802, 2023). "On the other hand, lymphocytes play a crucial role in cell-mediated immune destruction of cancer cells by activated T cells and other lymphocytes, while tumors can also release cytokines such as IFN-γ and TNF-α to regulate various immune functions in the body." (PMID 37841429, 2023). "By targeting inflammation and related prognostic biomarkers of cancer, including CRP and TNF-α, exercise holds promise for reducing and preventing CRF." (PMID 37507961, 2023). "Exosomes interact with cell surface receptors by carrying molecules, such as MHC–peptide complexes and tumor necrosis factor (TNF) ligands, which usually function as signal transduction in the immune response and induction of apoptosis in cancer cells." (PMID 37046653, 2023). "Aconitine alkaloids have been shown to promote the secretion of cytokines like TNF-α, IL-1β, and IFN-γ in cancer model mice, thereby enhancing the immune function of the body." (PMID 37180714, 2023).
cancer (continued). "The study showed that overexpression of TIM-3, lower TNF-α, and IFN-γ protein expressions in cancer tissue was relative to lymph node metastasis." (PMID 36865498, 2023). "To study this, we used the available time‐course data of four different cancer cell lines (A549, lung; DU145, prostate; OVCA420, ovarian; MCF‐7, breast) treated with TNF‐α (positive regulator of IP) and TGF‐β1 (negative regulator of IP)." (PMID 37097039, 2023). "The other pathways of upregulation in multiple cancer types are allograft rejection (n = 28), IL‐6/JAK/STAT3 signalling (n = 24), inflammatory response (n = 23), ROS pathway (n = 22) and TNF‐α signalling through NF‐kB (n = 14)." (PMID 37097039, 2023). "For instance, a recent MyxV bioengineered to express TNF and TNFSF14 demonstrated strong responses as a stand-alone cancer therapy and when combined with immunotherapy in several cancer models." (PMID 37835397, 2023). "Upregulated TNF-α in human TNBC stimulated the growth of the mammary molecules and activated many genes involved in the cancer cells’ growth, invasion, and metastasis." (PMID 37373025, 2023). "CpG-2722 induced the production of cytokines, including TNF-α, Trail, and IFN-γ, from immune cells, which in turn activated PS exposure on cancer cells." (PMID 37324949, 2023). "NK cells incubated with target cancer cells expressing NA-Fc4 had an increase over control cells in TNF-α and IFN-γ staining in the case of A549 cells but only in TNF-α staining for SKOV3 cells." (PMID 37146009, 2023). "In lung cancers, TAMs secrete IL-6 and TNFα in response to TLR2 activation by versicane, a proteoglycan produced by cancer cells." (PMID 37143666, 2023). "Tumor necrosis factor-α (TNF-α) can trigger caspase 8-mediated apoptosis of cancer cells and the combination of IFN-γ and TNF-α can induce senescence of cancer cells." (PMID 38077389, 2023). "From the network pharmacology analysis, it was found that the main targets for inhibiting BPH are AKT1, TNF, EGFR, STAT3 and PTGS2, which are enriched in pathways in cancer." (PMID 37446563, 2023). "The results of biological functional analysis indicated that 45 TFs were significantly present in numerous cancer-related pathways such as chemical carcinogenesis, MAPK signaling pathway, transcriptional misregulation in cancer, and TNF signaling pathway." (PMID 37733242, 2023). "Local delivery of anti–TNF-α neutralizing antibody rescues the pro-metastatic effects of β-catenin activation in AMs, and TNF correlates with CTNNB1 expression in the AMs of cancer patients." (PMID 37092550, 2023). "From the Elisa results, BMDCs in LT and LRT groups secreted higher amounts of IL-6, TNF-α, IL12p70, and IL-1β than in other groups, indicating the successful DCs maturation by upregulating CRT expression on cancer cell’s surface." (PMID 37951973, 2023). "PBMC from healthy donors were incubated with TNFα, TGFβ, rapamycin, PMA, EGF or with the conditioned media (CM) of cancer cells (HT-29), containing several TME factors, including cytokines, growth factors and chemokines." (PMID 37426665, 2023). "The higher levels of plasma VEGF-A, TNF-α, CCL2, IL-6, and IFN-γ were depicted in the Untreated Cancer TIF1-γ-DM group than in the Non-cancer TIF1-γ-DM group." (PMID 36357631, 2023). "Next, we performed gene set enrichment analysis and found that genes related to “osteoclast differentiation,” “TNF signaling pathway,” “JAK-STAT signaling pathway,” and “PD-1 and PD-L1 checkpoint” in cancer tissues were enriched in UBC9hi PCa subjects." (PMID 36626227, 2023). "Neutrophils can release NO, ROS, TNF, TNF-related apoptosis-inducing ligands (TRAIL), and cytolytic defensins to promote cancer cell death." (PMID 37371127, 2023). "We found that the expressions of TNF-α and IFN-γ in cancer tissues were lower than those in paracancerous tissues and normal tissues." (PMID 36865498, 2023).
cancer (continued). "In CCA etiology, assessment of TNF-α is varied; it promoted cancer cell invasiveness by MMP-9 through the activation of MAPK and ERK1/2 with cancer cell by MMP-9 through the activation of MAPK and ERK1/2 with metabolites FAK and COX-2." (PMID 36768732, 2023). "Regarding other types of cancer, the best-characterized cytokines that mediate MSCs homing to tumors include CXCL12, IFN-γ, IL-6, IL-8 and TNF, as well as growth factors such as TGF-β, HGF, PDGF and VEGF." (PMID 37563650, 2023). "Through cell-mediated apoptosis and immune processes, tumor necrosis factor-α (TNF-α) was a complex connector between inflammation and cancer." (PMID 37274025, 2023). "The PANoptosis score was positively correlated with many malignant pathways in pan-cancer, especially IL6-JAK-STAT3 signaling, interferon-gamma response, inflammatory response, IL2-STAT5 signaling, and TNF-a signaling via NF-kB signaling." (PMID 36890219, 2023). "This is further recapitulated in ingenuity pathway analysis (IPA), as enriched terms to psPD represent several immune response pathways driven by TREM1, TNF, IFNG, IL1, and IL6 while PD was primarily demarcated by E2F-mediated cancer activity." (PMID 38049893, 2023). "Further, TNF-α upregulated Snail, Slug, ZEB 1⁄2, and Twist 1 are dependent on NF-κB activation and lead to cancer cell epithelial-mesenchymal transition, shown to be related to increased invasion and metastasis." (PMID 36980727, 2023). "Adiponectin, leptin, IL-6, TNF-α, YKL-40 (chitinase-3-like-protein-1), osteopontin, and plasminogen activator inhibitor-1 (PAI-1) are all produced by adipocytes and stimulate cancer growth, progression, and metastasis." (PMID 37229273, 2023). "NF-κB signalling has been shown to activate the expression of various inflammatory mediators, such as IL1β, TNF and IL6, which promote cancer development." (PMID 36899924, 2023). "Proinflammatory cytokine secretion including TNF-α and IFN-γ assists CD8+ T cell-mediated cancer elimination." (PMID 37875481, 2023). "KEGG analysis showed that they were mainly enriched in cancer pathways, PI3K Akt signaling pathway, TNF signaling pathway, NF kappa B signaling pathway, TGF beta signaling pathway." (PMID 37589542, 2023). "NK cells (CD56+) function through the release of cytotoxic proteins to destroy cancer cells and virus infected cells, secrete IFN-γ and TNF-α that act on macrophages and dendritic cells and regulate (activate or inhibit) the response against specific antigens." (PMID 37527263, 2023). "Activation of the TNF-α/TNFR2 axis can promote the immunosuppressive phenotype and function of Tregs, leading to cancer progression." (PMID 36967783, 2023). "Few articles investigated the predictive value of inflammatory biomarkers [interleukin (IL)-1β, IL-6, IL-10, TNF-α, and MMP-2 and -9] in the peritoneal fluid of cancer patients who underwent surgery and experienced AL in different locations." (PMID 37601530, 2023). "Recently, Augoff's group also exhibited that MLN4924 possessed a significantly inhibitory efficacy on the tumor necrosis factor-alpha (TNF-α)-induced activity of MMP9 in ESCC cells, which further inhibited MMP9-dependent cancer cell migration." (PMID 37771770, 2023). "An exception to this is the MCF‐7 cell line, which showed increased IP expression even after removal of TNF‐α at 8 h, and increased IP expression with TGF‐β1 treatment (in contrast to other cancer cell lines )." (PMID 37097039, 2023). "In epithelial and mesenchymal cells, during ischemia-hypoxia, inflammation and cancer, its expression is up-regulated, and relevant agents are growth factors (VEGF-C and TGF-β1), cytokines (TNF-α, IFN-γ, IL-1 and IL6), fibronectin and lipopolysaccharides." (PMID 36829453, 2023).
cancer (continued). "We found that CD68, TNFα, and OTUD1 expression was inversely correlated with the overall survival of cancer patients." (PMID 37872170, 2023). "Notably, the poor-prognostic genes were significantly overrepresented among the 198 hallmark genes (41.92%, p-value = 8.11 × 10–23, Fisher's exact test), suggesting that the detrimental characteristics of the genes identified by the pan-cancer model may be inherited from the NFκB/TNF hallmarks." (PMID 37475016, 2023). "Previous studies proposed that under pathological conditions, TNF-α promoted cellular angiogenic activity through its capability to induce transcriptional activation of VEGF and its receptors, leading to cancer initiation." (PMID 37507468, 2023). "The proteins are also involved in a variety of different cancer signaling pathways, including IL17, TNF, NF-kappa B, PI3K-Akt, TGF-beta, MAPK, Rap1, and HIF-1 signaling pathways." (PMID 37209815, 2023). "Other EMT inducers, such as EGF and TNF-α, have also been targeted for therapies with the goal of attenuating EMT and cancer metastasis." (PMID 38067396, 2023). "This promotes high levels of secretion of pro-inflammatory cytokines such as tumor necrosis factor-alpha (TNF-α), interleukin-7 (IL-7), and interleukin-12 (IL-12), strengthening the immune system’s surveillance and clearance of cancer cells." (PMID 37609372, 2023). "Given the known dual role of TNF-α in regulating pro-survival and pro-apoptotic signals in cancer cells, we further explored the effect of SCEL on the molecular signaling regulated by TNF-α in lung-tropic LC cells." (PMID 38037106, 2023). "It has been previously proven that TNF-α, IL-6, and IFN-γ play decisive roles in the response of immune cells against cancer cells." (PMID 37226233, 2023). "The activated signaling pathways were PI3K‐Akt, Hippo, pathway in cancer, TGF‐β, VEGF, Rap1, HIF, MAPK, Ras, and TNF signaling." (PMID 37085918, 2023). "Significantly higher levels of plasma VEGF-A, TNF-α, CCL2, IL-6, and IFN-γ were observed among Cancer TIF1-γ-DM patients, especially among untreated Cancer TIF1-γ-DM patients." (PMID 36357631, 2023). "While the intricate molecular pathways governed by TNF-α remain partially elucidated, targeting TNF-α inhibition emerges as a promising avenue in cancer therapy." (PMID 38068717, 2023). "The ability of plasma VEGF-A, TNF-α, CCL2, IL-6, and IFN-γ levels to distinguish the presence of cancer was evaluated through the area under the curve (AUC) analysis." (PMID 36357631, 2023). "The results showed that cancer cells are characterized by lower expression levels of TLR4, TGF-β1, IFN-γ, and TNF-α, and that TLR4 expression was identical in low- and high-grade cancer." (PMID 40778061, 2023). "In patients with a cancer diagnosis 2–5 years prior and refractory IBD, anti-TNF or vedolizumab monotherapy can be considered when therapy is resumed." (PMID 36831424, 2023). "Mechanistically, TNF‐α and IFN‐γ induce cancer cell death by activating crucial molecules in PANoptosis, such as GSDMD, caspase‐3/8/7, and MLKL." (PMID 38069556, 2023). "Infiltrating cytotoxic T cells (CTLs) initiate the immune attack on cancer cells by releasing granzymes, perforin, interferon γ (IFN-γ), and tumor necrosis factor α (TNF-α)." (PMID 37111629, 2023). "In 54 SSc patients, there were significantly increased serum levels of IL-6, TNF-α, monocyte chemoattractant protein 1 (MCP1) (cancer-promoting), but also reduced IFN-γ and macrophage derived chemokine (MDC) (cancer-suppressive)." (PMID 37681925, 2023). "Other cancer-related genes and biological processes are enriched in accelerated genomic regions of elephants including FANCL and TNF-mediated signaling pathway." (PMID 36797268, 2023).